BRCA1 (BRCA1 DNA repair associated)
Diseases named in the same sentence as BRCA1 in open-access papers (continued):
Sharing a sentence is not in itself a finding about the gene and the disease.
liver disease (2 papers, 2025). "This study mimics the metabolic environment of metabolic dysfunction-associated steatotic liver disease (MASLD) and diabetic mellitus (DM) to investigate the function of BRCA1 in regulating glucose and lipid metabolism in hepatocytes under high glucose (HG) settings." (PMID 40138287, 2025).
lobular intraepithelial neoplasia (2 papers, 2012 to 2017). "Therefore, it is recommended that women with atypical ductalhyperplasia or lobular neoplasia undergo screening in a mannersimilar to that recommended for women with BRCA1 or BRCA2 genemutations." (PMID 28894332, 2017).
Long QT Syndrome (2 papers, 2024 to 2025). "In previous work on the KCNH2 variant p.Gly584Ser, which increases risk of long QT syndrome, and on BRCA1 p.Val1736Ala, we similarly identified carriers in our Northern Isles research populations who could not have been ascertained from family-based cascade testing." (PMID 39438716, 2024). "Examples in the Northern Isles include a pathogenic BRCA1 founder variant that has drifted to high frequency in Orkney, and an actionable KCNH2 Long QT Syndrome variant in Shetland." (PMID 39438716, 2024).
Luminal B (2 papers, 2022). "For instance, BRCA1-633delC was detected with relatively higher prevalence in patients with TNBC, whereas BRCA2-1466delT was found mainly in Luminal B tumors, but not in TNBC patient." (PMID 35858847, 2022).
malignant glioma (2 papers, 2016 to 2022). A grade III or grade IV glioma arising from the central nervous system. "To explore the therapeutic potential of targeting the BRCA1-RRM2 signalling axis in malignant gliomas, we performed immunohistochemistry (IHC) analysis BRCA1 and RRM2 in 145 gliomas and 10 non-neoplastic adult brain controls (NB)." (PMID 27845331, 2016).
myelogenous leukemia (2 papers, 2022 to 2024). "Although the specific E3 ligase responsive to phosphorylation of NSD2 in MM remains unidentified, breast cancer 1 (BRCA1) was found to act as an E3 ligase to support NSD2 degradation in the human myelogenous leukemia cell line K56298." (PMID 39394462, 2024).
ovarian cystadenocarcinoma (2 papers, 2023 to 2025). An adenocarcinoma that arises from the ovary and is characterized by the presence of cystic structures. "The first one describes the case of a 61-year-old woman with BRCA1 mutated ovarian cystadenocarcinoma and no previous history of abnormal liver function." (PMID 41586430, 2025).
ovarian endometrioid carcinoma (2 papers, 2023 to 2025). "We evaluated both WES and WGS data for homozygous deletions and identified losses in multiple genes known to be altered in ovarian endometrioid carcinomas, including PTEN, NF1, ARID1A, BRCA1, and others." (PMID 40981433, 2025).
Pan (2 papers, 2022 to 2023). "Pan-cancer, deleterious BRCA1/2 alterations were detected in 4% of the tumors, while 18% of the tumors were HRD-positive (HRDsum ≥ 42)." (PMID 35681079, 2022). "Pan-cancer, tumors with biallelic deleterious alterations in BRCA1/2 were separated strongly from tumors without relevant alterations (AUC = 0.89), while separation for tumors with monoallelic deleterious BRCA1/2 alterations was weak (AUC = 0.53)." (PMID 35681079, 2022).
Pca (2 papers, 2019). "In spite of the fact that germline Breast Cancer Associated (BRCA) mutations are quite uncommon in Pca (0.44% for BRCA1 and 1-2% for BRCA2), there are other epigenetic alterations affecting genes involved in DNA repair mechanisms, particularly homologous recombination repair (HRR) pathway." (PMID 31102368, 2019). "Although PARP inhibitors have been found to be synthetically lethal in cells not expressing BRCA1/2, such mutations are not frequent in many tumors, including PCa malignant cells." (PMID 31102368, 2019).
Pleural effusion (2 papers, 2008 to 2019). The presence of an excessive amount of fluid in the pleural cavity. "We postulated that BRCA1/2 mutation analyses from cancer cells derived from cytological samples like ascites, pleural effusion and enlarged lymph nodes would be concordant with BRCA1/2 mutation analyses from FFPE tumor tissue." (PMID 30940100, 2019). "Both ERCC1 and BRCA1 were negatively correlated with cisplatin sensitivity in pleural effusions of NSCLC patient." (PMID 18402708, 2008).
rectal adenocarcinoma (2 papers, 2020 to 2022). "One single publication reported a young male patient with a BRCA1 germinal variant who presented with rectal adenocarcinoma and showed an excellent response to oxaliplatin-containing neoadjuvant therapy." (PMID 35280729, 2022).
rhabdomyosarcoma (2 papers, 2021 to 2022). A rare aggressive malignant mesenchymal neoplasm arising from skeletal muscle. "Consistently, BRCA1 knock down also sensitized rhabdomyosarcoma cells to ATR inhibition." (PMID 35879366, 2022). "We hypothesized that due to its effect on BRCA1 phosphorylation and HR activity, pharmacological ATR inhibition could sensitize rhabdomyosarcoma cells to PARP1 inhibition." (PMID 35879366, 2022). "This confirmed that in the absence of BRCA1, rhabdomyosarcoma cells are sensitive to PARP-trapping." (PMID 35879366, 2022).
synovial sarcoma (2 papers, 2016 to 2022). "BRCA1 expression was associated with shorter DSS in synovial sarcoma and shorter EFS in malignant peripheral nerve sheath tumor." (PMID 27643881, 2016).
testicular cancer (2 papers, 2019 to 2024). A primary or metastatic malignant neoplasm that affects the testis. "Only 2 individuals (3%) presented cancer outside the BRCA1/2 spectrum, with testicular cancer." (PMID 38566764, 2024).
testicular tumor (2 papers, 2023 to 2025). "Rare entities such as penile and testicular tumors displayed distinct mutation patterns, including BRCA1/2 and MMR gene alterations." (PMID 41395625, 2025). "Genetic mutations of DNA damage repair genes such as BRCA1, which are known to cause MA, may also lead to testicular tumors." (PMID 37843278, 2023). "In LCT specimens of the proband, low levels of BRCA1 and RBBP7 were observed, leading to an impaired DSB repair system and increased risk for testicular tumor development." (PMID 37843278, 2023). "We also tested the BRCA1 expression in seminiferous tubules and testicular tumor tissue and found that BRCA1 was obviously decreased in the proband." (PMID 37843278, 2023).
thymoma (2 papers, 2021 to 2024). A neoplasm arising from the epithelial cells of the thymus. "For patients with types A and B1/B2 thymoma (n = 9), seven gene mutations, including MTOR, BRCA1, APC, NF1, HRAS, NTRK3, and PTCH1, were detected, and each gene appeared only once in patients with non-TCs+type B3 TETs." (PMID 34307137, 2021). "Few literature observations, mainly BRCA1/2 and ATM, are available about single case or families with sporadic/recurrent thymomas." (PMID 39273507, 2024).
thyroid autoimmune disease (2 papers, 2019 to 2025). "BRCA1 may be associated with thyroid autoimmune disease and affect cancer development through this route." (PMID 40361383, 2025).
tubular adenoma (2 papers, 2024 to 2025). A usually polypoid neoplasm arising from the glandular epithelium. "Sanger sequencing of the BRCA1 and RNF43 variants in the tubular adenoma, SSL and CRC from person 010 showed evidence of LOH of the wildtype allele for both variants in the SSL and adenocarcinoma but not the tubular adenoma." (PMID 38063999, 2024).
uterine endometrioid carcinoma (2 papers, 2022 to 2025). "Only 3% were classified as variants of strong clinical significance in BRCA1 and BRCA2 of ovarian high-grade serous (HGSC) and uterine endometrioid carcinoma." (PMID 36010253, 2022).
Vestibular schwannoma (2 papers, 2023 to 2024). A vestibular schwannoma (also known as acoustic neuroma, acoustic neurinoma, or acoustic neurilemoma) is a benign, usually slow-growing tumor that develops from the VIIIth cranial nerve supplying the inner ear. "This is the first reported case of vestibular schwannoma in a patient with a germline mutation of BRCA1 and the first documented example of chemotherapy including olaparib to have shown efficacy for schwannoma." (PMID 36911580, 2023).
vulvar cancer (2 papers, 2015 to 2021). "Apart from these two transcription regulators, Zf5 a known interactor of Brca1 tumor suppressor, was also found enriched in all the previous studies used for comparison and in our vulvar cancer gene signature study." (PMID 26559525, 2015).
xeroderma pigmentosum group D (2 papers, 2013 to 2014). Any xeroderma pigmentosum in which the cause of the disease is a mutation in the ERCC2 gene. "Like excision repair cross complementing 1 (ERCC1), xeroderma pigmentosum group D and G (XPD, XPG), BRCA1 belongs to nucleotide excision repair (NER) system, which has been reported to be the mayor repair system that reduced platinum-induced DNA damage." (PMID 23497550, 2013).
acute leukemia (1 paper, 2024). A clonal (malignant) hematopoietic disorder with an acute onset, affecting the bone marrow and the peripheral blood.
acute pancreatitis (1 paper, 2020). An acute inflammatory process that leads to necrosis of the pancreatic parenchyma. "At the molecular level, meta-analysis of gene expression profiles of acute pancreatitis in caerulein-treated mice revealed that Bap1 and other DNA repair genes (Brca1/2 and Atm) are upregulated within hours in response to tissue damage." (PMID 32541668, 2020).
alcoholism (1 paper, 2017). "We find that disulfiram (Antabuse), an ALDH2 inhibitor in widespread clinical use for the treatment of alcoholism, selectively eliminates BRCA1/2‐deficient cells." (PMID 28729482, 2017).
anal carcinoma (1 paper, 2022). "A study evaluating a cohort of BRCA1 or BRCA2 pathogenic variant carriers mostly of Ashkenazy ancestry concluded that they may be prone to developing anal carcinoma and left-sided mucinous histology CRC." (PMID 35280729, 2022).
anaplastic oligodendroglioma (1 paper, 2019). A WHO grade III oligodendroglioma with focal or diffuse malignant morphologic features (prominent nuclear pleomorphism, mitoses, and increased cellularity). "Interestingly, BRCA1 was mutated in one patient diagnosed with GBM, and BRCA2 mutation was shown in one sample of anaplastic oligodendroglioma." (PMID 31882734, 2019).
Barrett's oesophagus (1 paper, 2025). "This study compares the National Institute for Health and Care Excellence's guidelines for BRCA1/2, which are genetic risk conditions, and Barrett's oesophagus (BO), a morphological risk condition." (PMID 39812114, 2025). "This essay seeks to understand this disparity in more detail using BRCA1/2, genetic risk diagnoses, and Barrett's oesophagus (BO), a morphological risk diagnosis, as case studies." (PMID 39812114, 2025).
bladder tumors (1 paper, 2017). "Although BRCA1 and BRCA2 alterations are relatively common in some tumors settings and have important implications for treatment selection, somatic alterations or expression changes (resulting from BRCA1 promoter methylation or other epigenetic events) are relatively uncommon in bladder tumors." (PMID 28346378, 2017).
bone osteosarcoma (1 paper, 2024). A usually aggressive malignant bone-forming mesenchymal neoplasm arising from the bone. "To this end, we initially depleted BRCA1 and RAD18 in human bone osteosarcoma cells (U2OS) and studied replication fork recovery by DNA fiber analysis." (PMID 38943334, 2024).
cleft lip (1 paper, 2021). Congenital defect in the upper lip where the maxillary prominence fails to merge with the merged medial nasal prominences. "While little is known about how DDR functions during palate development, recent studies have shown that while it is modest, there are BRCA1 and BRCA2 variants in non-syndromic cleft lip and palate patients." (PMID 33854442, 2021).
cleft palate (1 paper, 2021). Cleft palate is a fissure type embryopathy that affects the soft and hard palate to varying degrees. "An ectomesenchymal-specific deletion of Brca1 or Brca2 resulted in cleft palate due to attenuation of cell survival." (PMID 33854442, 2021). "Since we previously reported that both BRCA1 and BRCA2 are required for craniofacial bone formation, these two DDR components provide us with a premise to examine whether dysregulation of DDR via the BRCA1 or the BRCA2 pathway leads to cleft palate." (PMID 33854442, 2021). "Because cell death in pre-migratory neural crest cells frequently leads to craniofacial abnormalities, one might predict that increased cell death in pre-migratory neural crest cells may lead to cleft palate in Brca1 cKO and Brca2 cKO mutants." (PMID 33854442, 2021). "The aim of this study is to investigate the mechanistic connection(s) between a dysfunctional DDR, due to disruption of BRCA1/BRCA2 and cleft palate, using pharmacological and mouse genetic approaches to dissect the etiology of this craniofacial malformation." (PMID 33854442, 2021). "Our data indicate that maintaining genomic stability through the BRCA1 and BRCA2 DDR machinery may be key in preventing cleft palate." (PMID 33854442, 2021). "It remains to be determined whether TCOF1, BRCA1, and BRCA2 genetically interact in palate development, and for this reason it is important to study how these specific DDR-related elements are involved in the etiology of cleft palate." (PMID 33854442, 2021).
colon adenoma (1 paper, 2024). An adenoma that arises from the colon. "Nevertheless, the mere detection of a senescence-like cellular state, e.g., in BRCA1+/mut breast tissues (C14), colon adenomas (C17) and other malignancies, does not indicate whether these cells have a tumor-suppressive or pro-tumorigenic functional role." (PMID 38645221, 2024).
cystic hygroma (1 paper, 2024). A benign lymphatic neoplasm usually arising from the neck and characterized by cystic dilation of the lymphatic vessels. "Although with the development of next-generation sequencing technology, genetic variants such as SOX9, KDR, and BRCA1 are involved in the pathogenesis of cystic hygroma, the specific pathogenesis of cystic hygroma remains unclear." (PMID 38650036, 2024).
Dubowitz syndrome (1 paper, 2023). A rare multiple congenital syndrome characterized primarily by growth retardation, microcephaly, distinctive facial dysmorphism, cutaneous eczema, a mild to severe intellectual deficit and genital abnormalities. "She had originally been suggested to have Dubowitz syndrome and was genotyped as part of an effort to identify Dubowitz-associated genes, during which she was found to have compound heterozygous BRCA1 mutations." (PMID 38146508, 2023).
Duchenne muscular dystrophy (1 paper, 2012). Duchenne muscular dystrophy (DMD) is a neuromuscular disease characterized by rapidly progressive muscle weakness and wasting due to degeneration of skeletal, smooth and cardiac muscle. "Since MLPA is routinely used to detect large genomic deletions and successfully detected exon skipping events in Duchenne muscular dystrophy in cDNA, we performed a pilot study to evaluate its value for BRCA1 cDNA." (PMID 22350158, 2012).
emphysema (1 paper, 2021). "BRCA1 AQUA scores inversely correlated with FEV1 percent predicted (P = –0.730, P < 0.0001) and correlated with percent radiographic emphysema (P = 0.471, P = 0.03)." (PMID 33290275, 2021).
endometrial polyp (1 paper, 2017). A benign nodular lesion protruding above the surface of the endometrium. "Mean CA125 levels in BRCA1 mutation carriers were statistically different as compared to all study groups with the exception of endometrial polyps." (PMID 28182133, 2017).
endometrioid tumor (1 paper, 2022). A benign, borderline, or malignant epithelial tumor of the female reproductive system characterized by the presence of glands and/or cysts lined by neoplastic cells that resemble endometrial cells. "BRCA1/2 mutations were more commonly identified in serous epithelial cancers and a non‐endometrioid tumor, while patients with a mutation in genes other than BRCA mutations were seen in neither serous nor endometrioid tumor (p value = .001, p value = .007, respectively)." (PMID 35608067, 2022).
erythroleukemia (1 paper, 2022). Acute erythroid leukemia characterised by the presence of at least 50% erythroid precursors and at least 20% myeloblasts in the bone marrow. "A single spontaneous case of erythroleukemia has been reported in a Mx1-Cre–driven Brca1-deficient mouse model." (PMID 36346676, 2022).
familial colorectal cancer type X (1 paper, 2024). Hereditary nonpolyposis colorectal cancer characterized by the absence of germline mutations in DNA mismatch-repair genes. "Remarkably, this report showed that pathogenic mutations in both BRCA1 and RNF43 were inherited together and were associated with CRC in a family with a specific type of familial CRC known as familial colorectal cancer type X (FCCTX)." (PMID 39195204, 2024).
familial disease (1 paper, 2009). "The vast majority of familial disease is associated with a low penetrant polygenic aetiology that conveys lifetime risks somewhere below 30%, and only a small proportion are carriers of the highly penetrant mutations of BRCA1 or BRCA2, in whom the lifetime risks are quite substantial." (PMID 19457262, 2009).
Fanconi anemia complementation group (1 paper, 2020). "In the Fanconi anemia complementation group A (Fanca) and Fanconi anemia complementation group G (Fancg) deficient mice, whose Fancd2 activation and FA/Brca1 pathway functionality are abolished, the neuron number is reduced at the dorsal telencephalon 32,49." (PMID 33029090, 2020).
Fanconi-like syndrome (1 paper, 2024). A syndrome characterized by pancytopenia, immune deficiency and cutaneous malignancies. "Interestingly, homozygosity for certain BRCA1 nonsense variants is viable due to the alternative splicing isoform ∆11q that partially retains BRCA1 function and skips the downstream exon 11 nonsense variants, causing a Fanconi-like syndrome." (PMID 39518003, 2024).
frontotemporal dementia (1 paper, 2019). Frontotemporal dementia (FTD) comprises a group of neurodegenerative disorders, characterized by progressive changes in behavior, executive dysfunction and language impairment, as a result of degeneration of the medial prefrontal and frontoinsular cortices. "Thus, FUS pathology-mediated loss of BRCA1 may contribute to cognitive defects, particularly in FUS-associated frontotemporal dementia (FTD)." (PMID 31801573, 2019).
gout (1 paper, 2021). A condition characterized by painful swelling of the joints, which is caused by deposition of urate crystals. "The final nine surviving monocyte-specific differentially methylated CpG sites were mapped to eight genes (PRKCZ, CIDEC, VDAC1, CPT1A, BIRC2, BRCA1, STK11, and NLRP12) that have not previously been studied in the field of gout genetics." (PMID 33493135, 2021).